CDK4 (cyclin dependent kinase 4)
Diseases named in the same sentence as CDK4 in open-access papers (continued):
Sharing a sentence is not in itself a finding about the gene and the disease.
breast cancer (continued). "Presently, three CDK4/6 inhibitors (CDK4/6i), palbociclib, ribociclib, and abemaciclib, have gained FDA approval for the treatment of metastatic ER-positive, HER2-negative breast cancer in combination with hormone therapy." (PMID 38961064, 2024). "Palbociclib is another potent CDK4/6 inhibitor, and the PALOMA-2 trial demonstrated its effectiveness in first-line treatment for advanced HR+/HER2- breast cancer in postmenopausal women." (PMID 38256428, 2024). "Unfortunately, this clinical trial was designed before the introduction of Cyclin-Dependent Kinase 4/6 inhibitors, which have proven their significant advantage in terms of PFS and partially OS, thus delaying the need to introduce CT in luminal breast cancer." (PMID 38397990, 2024). "PI3K inhibitor alpelisib completely blocked the CDK4/6i resistant xenografts progression in both PIK3CA mutant and ER+/HER2-breast cancer." (PMID 37475713, 2023). "Here, we aimed to analyze the use of CDK4/6i and clinical outcome of patients with HR+/HER2− ABC at four certified German university breast cancer centers in clinical routine." (PMID 36876172, 2023). "Recently, selective CDK4/6 inhibitors have shown clinical success, particularly in treating advanced-stage estrogen receptor ER+/HER2− breast cancer." (PMID 38138549, 2023). "CDK4 and CDK6 are not only essential for G1 to S phase cell cycle transition, but also play a central role in the growth of HR+ breast cancer cells." (PMID 37296790, 2023). "Although the importance of CDK6 in CDK4/6i resistance is widely recognized, the mechanism of CDK6 overexpression remains largely unclear, especially in tumors other than breast cancer." (PMID 37452037, 2023). "Three drugs targeting CDK4/6 have been approved by the FDA to be used in HR-positive and HER2-negative breast cancers." (PMID 37759706, 2023). "Breast cancer cells expressing FGFR1, transduced with FGFR1 or amplified with FGFR1 were resistant to CDK4/6i." (PMID 37475713, 2023). "With the continuous development of endocrine targeting drugs, especially the emergence of selective cyclin-dependent kinase (CDK4/6) inhibitors, the overall survival time in patients with HR+HER2- advanced breast cancer has been greatly improved." (PMID 37483648, 2023). "The ‘‘YB-1-PARP1’’ loop was proven to play a crucial role in the CDK4/6i resistance of breast cancer, and blocking the factor in the ‘‘YB-1-PARP1’’ loop can enhance the sensitivity of CDK4/6i efficiency." (PMID 38037159, 2023). "To offer a glimpse into future clinical applications, we analyzed the gene expression of Pal targeted genes, CDK4 and CDK6, and Nif targeted genes STAT3 and CDK2 in breast cancer through the TNMplot database." (PMID 37752122, 2023). "Recently, the synergistic effect of CDK4/6 (cyclin kinase 4/6) inhibitors and anti-HER2 drugs in HER2+ breast cancer has been reported." (PMID 36602226, 2023). "Among them, CDK4/6 inhibitors belong to a group of targeted therapies, mainly targeting combined hormone therapy for hormone receptor-positive HER2-negative advanced breast cancer." (PMID 36966290, 2023). "In breast cancer, phase III randomized study has shown that the trial combination of CDK4/6 inhibitor therapy results in longer progression-free survival and a relatively higher quality of life." (PMID 37591827, 2023). "Resistance to endocrine therapy and CDK4/6 inhibitors, the standard of care (SOC) in estrogen receptor-positive (ER+) breast cancer, greatly reduces patient survival." (PMID 37914699, 2023). "For clinical relevance, public mRNA microarray data sets of early breast cancer were analyzed and PEG10 immunohistochemical staining was performed using pre-CDK4/6 inhibitor tumor samples." (PMID 38017459, 2023).
breast cancer (continued). "To mimic RB1 loss-of-function alterations, we used CRISPR-Cas9 to delete RB1 in CDK4/6i sensitive MCF-7 and T47D breast cancer cells." (PMID 37502925, 2023). "The potential benefits of the simultaneous inhibition of CDK4/6 and aromatase were observed in HR+/HER2- breast cancer as an outcome of enhanced significant G1-S cell cycle arrest." (PMID 36985460, 2023). "Further study showed that YAP-induced CDK6 upregulation was responsible for CDK4/6 inhibitor resistance, highlighting the central role and clinical value of CDK6 in breast cancer therapy." (PMID 37211598, 2023). "The use of a combination of CDK4 and CDK6 inhibitors (CDK4/6) with endocrine therapy for the treatment of HR+ and HER2− breast cancer improves overall survival, and increases the proportion of patients with a long-term response." (PMID 37958607, 2023). "Camizestrant also has potential, in combination with CDK4/6 and PI3K/AKT/mTOR inhibitors, to address resistance to current ETs: The highest unmet need in the largest group of patients with breast cancer." (PMID 37725704, 2023). "Recently, CDK4/6 inhibitors have entered the clinic and have shown promise in treating ER-positive and HER2-negative advanced breast cancers." (PMID 37483519, 2023). "CDK4/6 inhibitors are primarily used for hormone receptor positive, HER2-negative advanced breast cancer." (PMID 38352694, 2023). "CDK4/6 inhibitors combined with endocrine therapy have become the standard treatment strategy for HR‐positive, HER2‐negative advanced breast cancer." (PMID 38090370, 2023). "More importantly, we revealed that high MITH indicated cell cycle pathway activation in HR+ breast cancers and such activation was mainly due to the upregulation of Cyclin E/CDK2, which was an important mechanism of CDK4/6 inhibitor resistance." (PMID 37880211, 2023). "According to the results, SKACP003 was able to suppress the expression of CDK-4 and CDK-6 in breast cancer cell lines." (PMID 36770598, 2023). "CDK4 and CDK6 are members of a family of serine/threonine kinases that are activated by binding to cyclins (mostly cyclin D in breast cancer) and enhance cell cycle progression and cell proliferation." (PMID 37759706, 2023). "The currently developed CDK4/6 inhibitors, such as ribociclib, oalbociclib and abemaciclib, are mainly used to treat ER+/HER2− breast cancer and can significantly prolong the PFS of patients." (PMID 37864031, 2023). "Palbociclib is the first CDK4/6 inhibitor approved for HR‐positive, HER2‐negative advanced breast cancer." (PMID 38090370, 2023). "Usage of CDK4/6 inhibitors has led to improvement in PFS and OS in patients with HR+/HER2− advanced breast cancer." (PMID 37759823, 2023). "Thus, high PARP1 protein levels may be related to CDK4/6i resistance in breast cancer." (PMID 38037159, 2023). "Recent studies have shown that combined therapy with CDK4/6i and anti-HER2 antibodies prevents tumor recurrence in a transgenic mouse model of HER2-positive breast cancer." (PMID 38037159, 2023). "A selective CDK4/6 inhibitor, palbociclib, has shown outstanding results in phase II clinical trials in patients with estrogen receptor-positive HER2-negative breast cancer." (PMID 37781694, 2023). "The third generation of CDK inhibitors, which show preferential specificity for CDK4/6 over some other CDKs, have received regulatory approval from the United States FDA for use in the management of breast cancer." (PMID 36768557, 2023). "CDK4 and CDK6 have shown significant progress in inhibiting metastasis in individuals with metastatic ER+ breast cancer and are now in the adjuvant setting." (PMID 38022130, 2023). "ON123300, a multi-kinase inhibitor with high specificity for CDK4/CDK6 and NUAK1, showed a strong anti-tumorigenic effect on breast cancer, glioblastoma, lymphoma, and multiple myeloma and reduced Akt phosphorylation." (PMID 38135881, 2023).
breast cancer (continued). "Three selective CDK4 and 6 inhibitors, palbociclib, ribociclib, and abemaciclib, have been developed for clinical use in HR+, HER2− breast cancer." (PMID 36414795, 2023). "Recently, three CDK4/6 inhibitors palbociclib, ribociclib, and abemaciclib were approved for the treatment of patients with HR-positive, HER2-negative breast cancer." (PMID 37041169, 2023). "We also discuss selected trials with agents targeting the PI3K/AKT/mTOR and related pathways as well as the rationale supporting the clinical development of triple combination therapy targeting ER, CDK4/6 and PI3K/AKT/mTOR in ER+ advanced breast cancer." (PMID 36901954, 2023). "SKACP003-treated breast cancer cells showed decreased expression of Wnt/β-Catenin targeting genes such as C-Myc, P68, and COX-2 and significant downregulation of CDK-4 and CDK-6 genes." (PMID 36770598, 2023). "For instance, CDK4/6 inhibitors, such as palbociclib and ribociclib, have been approved by FDA for the treatment of breast cancer." (PMID 36741908, 2023). "Our data confirmed the sensitizing effect of a CDK4/6 inhibitor on lapatinib and suggested mechanisms by which lapatinib and palbociclib synergistically work against HER2 therapy-resistant breast cancer in a nude mouse model." (PMID 37160904, 2023). "FGFR is also a potential target for CDK4/6i resistance, as suppression of FGFR signaling was shown to reverse CDK4/6i resistance in HR + breast cancer." (PMID 38037159, 2023). "Earlier, we showed camizestrant has antitumor activity in twice as many ER+ breast cancer PDX models as fulvestrant, including those derived from tumors that are primary or metastatic, naïve or exposed to ET and/or CDK4/6i, and with different ESR1m status." (PMID 37725704, 2023). "CDK4/6 inhibitors can reverse the resistance of HER2-positive breast cancer to anti-HER2-targeted therapy and induce tumor cells to enter cell cycle arrest and have a senescent cell phenotype by inhibiting Rb and S6RP activity." (PMID 37251343, 2023). "Similar to CDK4/6 inhibitors, small molecule inhibitors of the PI3K/AKT/mTOR pathway are also FDA approved for use in endocrine resistant ER+/HER2-breast cancer in combination with ET." (PMID 37035239, 2023). "Palbociclib and abemaciclib have become extensively used in Japan, with CDK4 and 6 inhibitor/ET combination therapy now the standard of care for advanced HR+, HER2− breast cancer." (PMID 36414795, 2023). "We evaluated the anti-proliferative activity of palbociclib, the first approved CDK4/6 inhibitor for the treatment of patients with HR-positve, HER2-negative breast cancer, in these 6 lines of ESCC cells." (PMID 37041169, 2023). "The inhibitors of CDK4/6, palbociclib, ribociclib, and abemaciclib, are FDA- approved drugs to treat breast cancer in combination with endocrine therapy." (PMID 37414783, 2023). "Previous research has discovered that ZEB1 promotes breast cancer cell proliferation by down-regulating p21 and up-regulating CDK2 and CDK4 through the cell cycle." (PMID 37978168, 2023). "Palbociclib and other Cdk4/6 inhibitors are used clinically for the treatment for HR+ and HER2- breast cancers." (PMID 37977116, 2023). "Our previous study demonstrated that IGFBP-3 induced G1 cell cycle arrest by inhibiting cyclin D1, cyclin D3, cyclin E, cyclin A, CDK2, CDK4, total and phospho-pRb, and increasing p21 and p16 in MCF-7 breast cancer cells." (PMID 37253773, 2023). "Patients had received 0–3 prior lines of therapy for metastatic ER+/HER2-breast cancer, and 12-month PFS in this trial was 53% in patients who had received prior CDK4/6 inhibitor therapy." (PMID 37035239, 2023). "In recent years, immunotherapy and targeted drug use, including CDK4/6 and PI3K pathway inhibitors, have been on the rise in breast cancer treatment." (PMID 37251941, 2023).
breast cancer (continued). "Several studies have shown that some kinases founded in breast cancer, melanoma and hematopoietic malignancies are able to regulate the function of CDK6 and CDK4, which makes CDK6 an attractive target for therapeutic disruption." (PMID 36457244, 2023). "Among these, CDK4/6 inhibitors are approved to treat certain types of hormone receptor-positive, HER2-negative breast cancer in combination with endocrine therapy." (PMID 37059713, 2023). "Ribociclib is a highly selective and orally effective CDK4/6 inhibitor used for the treatment of HR + and HER2 − breast cancers with manageable toxicity profiles." (PMID 37415164, 2023). "The combination of anti-HER2 drugs and CDK4/6 inhibitors showed strong synergistic effects and high efficacy in HER2+ breast cancer cells." (PMID 36602226, 2023). "miR-107 was shown to negatively regulate NEAT1 expression and regulate breast cancer progression through affecting the tumor development-associated genes, including TIMP-1, PDGF-A, SERPINB2, cyclin D1, CDK4, and CPA1A in breast cancer cells." (PMID 37310654, 2023). "Many new CDK4/6i and HER2-targeted medication combination schemes are now being investigated for treating both ER+/HER2+ and HR+/HER2+ breast cancer." (PMID 38293701, 2023). "CDK4/6 inhibitors have shown a synergistic effect with anti-HER2 therapy in hormone receptor (HR)-positive and HER2-positive breast cancer (BC)." (PMID 37805496, 2023). "Cyclin-dependent kinase 4 and 6 inhibitors (CDK4/6is) have transformed the treatment of hormone receptor-positive (HR+) and human epidermal growth factor receptor 2-negative (HER2−) breast cancer over the last decade." (PMID 37759823, 2023). "To this end, we took advantage of MCF-7 (breast carcinoma) and AGS (gastric adenocarcinoma) cells, both of which retain a functional pRB pathway and are responsive to CDK4/6 inhibition." (PMID 37298236, 2023). "The PALOMA-3 study combined palbociclib, a CDK4/6 inhibitor, with fulvestrant, a selective ER degrader, to treat women with HR-positive, HER2-negative advanced breast cancer." (PMID 35887191, 2022). "Currently, three CDK4/6 inhibitors (Palbociclib (PD), Ribociclib (LEE), and Abemaciclib (LY)) have been approved by the FDA for the treatment of breast cancer." (PMID 35948546, 2022). "This is consistent with findings from an ongoing multicenter phase Ia FCN-437c monotherapy study in China that is enrolling women with HR+/HER2– advanced breast cancer (NCT04488107), as well as single-agent data reported for approved CDK4/6 inhibitors." (PMID 36291780, 2022). "Thirteen women who started alpelisib and ET at standard doses between 2018 and 2022 for advanced breast cancer (ABC), after undergoing CDK4/6i and everolimus treatment, were eligible for the study entry." (PMID 36292649, 2022). "Palbociclib, ribociclib, and abemaciclib are currently FDA-approved CDK4/6 inhibitors and are used in combination with endocrine therapies for the treatment of ER-positive/HER2-negative breast cancer." (PMID 36071983, 2022). "CDK4/6i has revolutionized the treatment of advanced HR+ MBC, and the indication has been expanded to early-stage breast cancer with remarkable results from the monarchE trial." (PMID 35804935, 2022). "To date, three CDK4/CDK6 inhibitors, palbociclib, ribociclib, and abemaciclib, have been applied in patients with breast cancer." (PMID 35804842, 2022). "CDK4/6 inhibitors are mainstay treatments for women with metastatic HR+, HER2- breast cancer and induce radiosensitization in preclinical models of ER+ breast cancer and TNBC." (PMID 36387071, 2022).
breast cancer (continued). "Several antagonists with excellent activity against CDK4 and CDK6 have been approved for treatment of breast cancer, which restore cell cycle control at the G1/S transition and significantly extend patients' lives." (PMID 35280504, 2022). "When used in combination with endocrine therapy, palbociclib, a CDK4 and CDK6 inhibitor, resulted in improved progression-free survival in ERα+/Her2-negative advanced breast cancer." (PMID 35205737, 2022). "The MONALEESA trials looked at the efficacy and safety of ribociclib, a CDK4/6 inhibitor, with a choice of endocrine partners as a first- or second-line treatment for patients with HR-positive, HER2-negative advanced breast cancer." (PMID 35887191, 2022). "Early evidence that CYCLIN D and CDK4/6 activities are upregulated in certain tumor cell types, and that cdk4-/- mice fail to develop MMTV-neu and MMTV-ras-induced mammary tumors, led to concerted efforts to develop small molecule inhibitors for these kinases." (PMID 36051751, 2022). "CDK4/6 inhibitors, targeting the direct binding partners of CCND1, show promise for ER+ breast cancer." (PMID 35523804, 2022). "Notably, cyclin-dependent kinase 4/6 (CDK4/6, cell cycle-related genes) inhibitors have shown significant activity against several cancers and some (namely palbociclib, ribociclib and abemaciclib) are approved for treatment of patients with advanced breast cancer." (PMID 35574406, 2022). "Mechanistically, there were confirmed binding sites between hsa_circ_0006014 and miR-885-3p, and hsa_circ_0006014 promoted breast cancer cell proliferation partially by sponging miR-885-3p and influenced CDK2/CCNE1 and CDK4/6/CCND1." (PMID 35383130, 2022). "The first CDK4/6 inhibitor, palbociclib, was described in 2004 and later approved by the FDA as a treatment for hormone receptor (HR) + HER2‐ breast cancer." (PMID 36065138, 2022). "Continuous inhibition of CDK4 and CDK6 by abemaciclib resulted in cellular senescence and apoptosis in human breast cancer cells and had broad antitumor activity in human tumor xenograft models." (PMID 34661821, 2022). "These compounds are predicted to stably interact with the MMP12, CDK4, JAK3, VEGFR2, MMP13, VEGFR1, and KCNA3 proteins, which have a role in inhibiting the growth and inducing apoptosis in breast cancer cells." (PMID 36106139, 2022). "The addition of CDK4/CDK6 inhibitors to ET markedly improves progression-free survival (PFS) over ET alone in patients with HR+, HER2− advanced breast cancer (ABC) and has become the new standard of care in this setting." (PMID 34661821, 2022). "Palbociclib is the first CDK4/6 inhibitor approved by Food and Drug Administration (FDA) of U.S. and implied in metastatic ER+/HER2− breast cancer." (PMID 37181790, 2022). "Blocking p27-Y88 phosphorylation by Brk-SH3 peptide efficiently inhibited CDK4 and CDK2 activity and arrested proliferation of breast cancer cells in a xenograft model." (PMID 35597806, 2022). "In this study, we constructed a novel fluorescent probe, CPP30‐Lipo/CDKACT4, for real‐time monitoring of CDK4 activity and the therapeutic efficacy of its inhibitor in HR+/HER2– breast cancer." (PMID 35711853, 2022). "The ATP-competitive small molecule compound palbociclib inhibits the enzymatic functions of CDK6 and CDK4 and has been FDA approved for the treatment of breast cancer patients." (PMID 35326705, 2022). "For example, targeting both CDK4 and CDK6 by palbociclib, ribociclib, abemaciclib, and trilaciclib is believed to increase the effectiveness in treating breast cancer." (PMID 36254250, 2022). "Breast cancers, particularly metastatic HR+/HER2− advanced breast carcinomas, are currently treated with CDK4/6I." (PMID 36358806, 2022). "Drugs targeting the cell cycle‐regulatory proteins CDK4 and CDK6 have been approved for the treatment of breast cancer, and inhibitors targeting other CDKs are currently in clinical trials." (PMID 35322916, 2022).